AUTS2 (activator of transcription and developmental regulator AUTS2)
Diseases named in the same sentence as AUTS2 in open-access papers (continued):
Sharing a sentence is not in itself a finding about the gene and the disease.
AUTS2 syndrome (17 papers, 2017 to 2025). "Pathogenic structural variants in AUTS2 gene include translocations, duplications, deletions or single-nucleotide polymorphisms (SNPs) and lead to the development of AUTS2 syndrome." (PMID 40943469, 2025). "Pathogenic variants in AUTS2 are associated with a neurodevelopmental disorder called the AUTS2 syndrome." (PMID 40658195, 2025). "One of these, known as cg25105066, belongs to the autism susceptibility candidate 2 (AUTS2) gene, which is an “Activator of Transcription and Developmental Regulator AUTS2” and an elite gene for “intellectual developmental disorder autosomal dominant 26”." (PMID 39584967, 2024). "As of 2021, more than 60 patients with pathogenic AUTS2 variants have been reported, and the AUTS2 syndrome has been well characterized as a neurodevelopmental and somatic malformation disorder with diverse phenotypes." (PMID 35431798, 2022). "In a study of mutations in AUTS2 syndrome, the interaction of AUTS2 with P300 in HEK 293 cells was found to be disrupted by mutations involving the HX repeat." (PMID 35431798, 2022). "In contrast, deletions of the C-terminus of AUTS2 are mostly associated with a severe AUTS2 syndrome phenotype combining neurodevelopmental features with malformations and dysmorphic features." (PMID 34805182, 2021). "To date, more than 60 patients with AUTS2 syndrome have been described in the literature and most of them carry an intragenic de novo deletion of AUTS2, whereas point mutations leading to the disease are rarely described." (PMID 34805182, 2021). "Mutations in AUTS2 cause a human developmental disorder, AUTS2 syndrome, we therefore investigated variant load in large control human populations for each AUTS2 family gene." (PMID 33306672, 2020). "AUTS2 syndrome is caused by pathogenic variants in AUTS2, a paralogous gene of FBRSL1." (PMID 40658195, 2025). "One hypothesis is that AUTS2 deficiency within the developing hippocampus may underlie ID in AUTS2 syndrome patients." (PMID 35431798, 2022). "The development and comparison of additional brain region-specific COs coupled with advanced technological tools to investigate various patient AUTS2 variants can start to uncover neurobiological functions that contribute to the clinical heterogeneity observed in AUTS2 syndrome patients." (PMID 35431798, 2022). "It is possible that similar molecular mechanisms that perturbs DG neurogenesis in AUTS2 deficient mice, may contribute to neocortical growth defects in human AUTS2 syndrome patients." (PMID 35431798, 2022). "Taken together, this evidence implies that the deletion of the C-terminal region of full-length AUTS2 transcript and/or the loss of expression of C-terminal AUTS2 short transcripts may contribute to the onset of AUTS2 syndrome." (PMID 35011572, 2021). "The functional significance of the C-terminal region is supported by human studies and animal models; it is associated with more severe forms of AUTS2 syndrome in humans, and administration of the C-terminal transcript of human AUTS2 rescued the phenotype in a zebrafish Auts2 MO knockdown." (PMID 33306672, 2020). "Interestingly, mutations in the FBRSL1 paralogue AUTS2 lead to an intellectual disability syndrome (AUTS2 syndrome)." (PMID 32424618, 2020). "As noted, a wide range of neurodevelopmental phenotypes in the patients with AUTS2 syndrome have been reported in individual studies; however, few studies have systematically reviewed the relationship between genotype and phenotype using a relatively large cohort of patients with AUTS2 mutations." (PMID 35011572, 2021). "Therefore, defects in neuronal migration and neuritogenesis due to loss of AUTS2 function in the cytoplasm may partly reflect the complex phenotypes of AUTS2 syndrome." (PMID 35011572, 2021).
AUTS2 syndrome (continued). "These pathways, coupled with the translocation’s selective effects on Auts2 isoforms and coordinated dysregulation of Galnt17, suggest novel hypotheses regarding the etiology of the human “AUTS2 syndrome” and the wide array of neurodevelopmental disorders linked to variance in this genomic region." (PMID 31554716, 2019). "Their paradigm revealed that the patients with deletions of the conserved C-terminal regions of AUTS2 (exons at the 3′ of the AUTS2 gene) showed severe AUTS2 syndrome phenotypes including neurodevelopmental disorders and dysmorphic features." (PMID 35011572, 2021). "This is likely correlated with the observation that the severity of the symptoms of AUTS2 syndrome is prominent in individuals with disruption at the 3′ end of the AUTS2 locus." (PMID 35011572, 2021). "A review of the literature retrieved seven studies reporting on 31 patients with AUTS2 syndrome with ASSS values and an AUTS2 pathogenic variant." (PMID 34573342, 2021). "Our patients presented with features of the AUTS2 syndrome and additional symptoms, suggesting that mutations in FBRSL1 produce a more complex phenotype than mutations in the paralogue AUTS2." (PMID 32424618, 2020). "Autism susceptibility candidate 2 (AUTS2) is a neurodevelopmental regulator associated with an autosomal dominant intellectual disability syndrome, AUTS2 syndrome, and is implicated as an important gene in human-specific evolution." (PMID 33306672, 2020). "Although Galnt17 mutations have not been investigated, several phenotypes detected in 16GsoT/T mice overlap obviously with those of Auts2 KO mutants, and share features with human AUTS2 syndrome patients as well." (PMID 31554716, 2019). "Many phenotypic features are characteristic of Auts2 gene KO mice and patients with AUTS2 syndrome." (PMID 40943469, 2025). "Single-cell chromatin profiling of AUTS2 syndrome organoid models could extend our understanding for the role of the PRC1-AUTS2 complex in epigenetically heterogeneous cell populations." (PMID 35431798, 2022). "Auts2 conditional knockout mouse models are invaluable for dissecting the circuit mechanisms that may contribute to phenotypes observed in AUTS2 syndrome." (PMID 35431798, 2022). "Heterozygous disruption of Auts2 results in similar symptoms as seen in AUTS2 syndrome patients including growth reduction, defects in communication, exploratory behavior as well as learning and memory, while social behavior and sensor motor gating functions were normal." (PMID 34805182, 2021). "AUTS2 syndrome (MIM 615834) was first described in 2013, as a neurodevelopmental disorder caused by pathogenic variants and deletions of the AUTS2 gene (MIM 607270, activator of transcription and developmental regulator)." (PMID 34805182, 2021). "In humans, it has been reported that the severity of the pathological features of the AUTS2 syndrome is higher in individuals with the deletions of exons at the 3′ of the AUTS2 locus compared to the different combinations of in-frame deletions of exons 2–5 at the 5′ region." (PMID 28505103, 2017). "Notably, this phenotype was observed in Auts2 heterozygous cKO mice, which may mimic the pathology of human AUTS2 syndrome patients." (PMID 39815005, 2025). "Therefore, it was suggested that the AUTS2 C-terminus plays a critical role in AUTS2 syndrome." (PMID 34805182, 2021). "Similarly, behavioral studies in various knock-out mutants have clearly established a link between Auts2 and behavior, suggesting a major role of this gene in controlling vertebrate neurodevelopment and behavior consistent with our current understanding of the AUTS2 syndrome." (PMID 40346605, 2025). "Further investigation of AUTS2 function using immunofluorescence techniques and sc-RNA seq will provide deeper understanding for the role of AUTS in IP and ORG populations in human corticogenesis and in AUTS2 syndrome." (PMID 35431798, 2022).
AUTS2 syndrome (continued). "Meanwhile, the individuals carrying a frame shift microdeletion within exon 6 or 7, which would only disrupt full-length AUTS2 transcript but were unlikely to affect the C-terminal AUTS2 short transcripts, have reportedly exhibited severe AUTS2 syndrome phenotypes." (PMID 35011572, 2021).
schizophrenia (14 papers, 2015 to 2024). A major psychotic disorder characterized by abnormalities in the perception or expression of reality. "This suggests a mechanistic model in which the genetic regulation of RERE and its downstream effect on AUTS2 in astrocytes contribute to schizophrenia susceptibility." (PMID 39711543, 2024). "Moreover, it has recently been reported that AUTS2 is also associated with schizophrenia as well as drug dependence including alcohol and heroin." (PMID 26717414, 2015). "However, it has been shown that alteration in methylation levels on the CALN1 and the AUTS2 gene occur in schizophrenia patients." (PMID 30787867, 2019). "For example, exonic deletions in the neurodevelopmental gene AUTS2 are often associated with cognitive deficits, and variants in CSMD2 have been associated with comorbidity of depression and alcohol dependence, and schizophrenia." (PMID 26829228, 2016). "Previously, many candidate genes, including NRG1 (encoding neuregulin 1), AUTS2 (autism susceptibility candidate 2), TSPAN8 (Tetraspanin-8), ZNF804A (zinc-finger protein 804A), among others, have been identified that might confer risk for schizophrenia." (PMID 26016498, 2015).
dyslexia (8 papers, 2011 to 2024). A learning disorder characterized by an impairment in processing written words. "Two unrelated children (2/322, 0.6%) with dyslexia carried CNVs encompassing AUTS2, both inherited from a parent." (PMID 22102821, 2011). "While the phenotype of dyslexia segregated with the AUTS2 duplication in the first family, in the second family the deletion was inherited from affected grandmother through unaffected father." (PMID 22102821, 2011). "In addition, the AUTS2 and SH2B3 dyslexia-disposing variants were associated with higher volume in the optic radiation." (PMID 39693421, 2024).
Anxiety (4 papers, 2015 to 2022). Intense feelings of nervousness, tension, or panic often arise in response to interpersonal stresses. "Besides, its downregulation in Drosophila reduces sensitivity to alcohol, thus possibly increasing consumption, while in mice deficient in AUTS2, a decrease in anxiety-related behaviors is evident." (PMID 34201295, 2021). "Behavioural phenotypes observed in Auts2 heterozygous mutant mice are characterized by lower anxiety-like behaviour and impaired memory." (PMID 30723624, 2019). "We found that Auts2 heterozygotic mutant mice displayed behavioral abnormalities in anxiety-related emotions and memory functions, indicating the role of AUTS2 in the acquisition of neurocognitive function as well as cortical development." (PMID 26717414, 2015). "Together, these results suggest that AUTS2 plays an important role for high-order brain functions such as anxiety-related emotional behaviors as well as in certain types of memory formation." (PMID 26717414, 2015). "Auts2-deficient mice displayed a decrease in exploratory behavior as well as lower anxiety-like behaviors in the absence of any motor dysfunction." (PMID 26717414, 2015). "Hence, it may be speculated that AUTS2 not only affects anxiety and alcohol consumption in inverse directions, but, as a result of altered function, produces higher anxiety levels and subsequent alcohol misuse induced by the self-medication mechanism." (PMID 34201295, 2021). "Consistent with human cases, we found in this study that heterozygotic disruption of Auts2 alone sufficiently induced several behavioral abnormalities including decrease of exploratory behaviors in a new circumstance as well as the decrease of anxiety against aversive situations for mice." (PMID 26717414, 2015).
cognitive deficits (4 papers, 2015 to 2019). "Mutations in AUTS2 give rise to a host of cognitive impairments (see Oksenberg and Ahituv, 2013 for review)." (PMID 26283924, 2015). "Finally, RUNX2 is also functionally related (via AUTS2) to CBL, in turn linked to Noonan syndrome-like disorder, a condition involving facial dysmorphism, a reduced growth, and several cognitive deficits." (PMID 26283924, 2015).
leukemia (3 papers, 2016 to 2023). A malignant (clonal) hematologic disorder, involving hematopoietic stem cells and characterized by the presence of primitive or atypical myeloid or lymphoid cells in the bone marrow and the blood. "Although several studies reported its possible function in lymphoma or leukemia, the mechanistic role of AUTS2 in cancer remains largely unclear." (PMID 37679762, 2023). "Thus, a network linking MEF2C, IL7R, STAT5 and AUTS2 may play a role in two cellular contexts: T-cell differentiation/leukemia and brain development/autism-related disorders." (PMID 27322685, 2016). "Our data suggest synergistic inputs of AUTS2 and MEF2C in lymphopoiesis and leukemia (de)regulating NKL homeobox gene MSX1." (PMID 27322685, 2016).
neuroblastoma (3 papers, 2017 to 2024). Neuroblastoma (NB) is the most common solid, extracranial childhood tumor. "Nevertheless, our bioinformatic analysis of datasets available on R2 platform stress out the importance of different isoforms of AUTS2 in patients with neuroblastoma." (PMID 38495105, 2024). "The cytoplasmic AUTS2 promotes lamellipodia formation in neuroblastoma cells and neurite extension of hippocampal primary cultured neurons in vitro." (PMID 28505103, 2017). "Interestingly, we also stress the importance of AUTS2 in neuroblastoma by presenting its mRNA positive correlation with survival of neuroblastoma patients." (PMID 38495105, 2024). "Similarly, the activation of Rac1 observed after AUTS2 overexpression in N1E-115 mouse neuroblastoma cells (the “AUTS2-Rac1 pathway”) may also be explained, at least in part, by AUTS2 regulation of transcripts Prex1 and Rasgrf2, which were significantly reduced in Auts2del15/del15 neocortex." (PMID 35431798, 2022). "The mechanism by which PHLDA1 is involved in regulation of neuroblastoma differentiation might relay on its direct interaction with DCAF7/AUTS2 complex, what might lead to alteration in the AUTS2 isoforms balance observed in this study." (PMID 38495105, 2024).
acute lymphoblastic leukemia (2 papers, 2017 to 2024). Leukemia with an acute onset, characterized by the presence of lymphoblasts in the bone marrow and the peripheral blood. "The AUTS2 gene, implicated in the neurodevelopmental process and acute lymphoblastic leukemia, was also noted." (PMID 38183082, 2024). "Finally, AUTS2 is involved in translocations with PAX5 in B-cell precursor acute lymphoblastic leukemia and other cancers." (PMID 29166413, 2017).
breast carcinoma (2 papers, 2015 to 2019). "Additionally, we previously reported decreased XIST and AUTS2 mRNA expression in breast cancer cells as a result of forced ACSL4 expression." (PMID 26636648, 2015). "Two coding genes, AUTS2 and GALNT17, were located within a 500 MBp window around the 45 highly correlated variants, but the expression of neither of the two was associated with breast cancer survival in KMplotter analyses of TCGA data." (PMID 30787463, 2019).
focal epilepsies (2 papers, 2010 to 2011). "In addition, we also identified a 354 kbp deletion encompassing AUTS2 in one individual with idiopathic ID, pervasive developmental delay, partial epilepsy, and left hemihypertrophy." (PMID 22102821, 2011).
juvenile myoclonic epilepsy (2 papers, 2010 to 2011). "More recently, unique AUTS2 deletions and duplications were observed in Juvenile Myoclonic Epilepsy and ADHD." (PMID 22102821, 2011).
melanoma (2 papers, 2023 to 2024). A malignant, usually aggressive tumor composed of atypical, neoplastic melanocytes. "Among them, 6 genes (NPTX1, AUTS2, RPS6KA2, KAT2B, MYO5A and HMG20B) were simultaneously downregulated in the melanoma samples compared with the noncancerous samples in GSE31909 and GSE35388 microarray data." (PMID 37384727, 2023).
Williams-Beuren syndrome (2 papers, 2021 to 2022). "Recurrent breakage at this fragile site has been implicated in the Williams-Beuren syndrome and and this region contains the genes LIMK1, EIF4H(WBSCR1), AUTS2 as well as the tumor suppressor gene FZD9." (PMID 33444353, 2021).
B cell precursor acute lymphoblastic leukemia (1 paper, 2017). "Also, it is interesting to note, in the context of the ASD/cancer connection, that AUTS2 is part of a translocation commonly found in childhood B cell precursor acute lymphoblastic leukemia." (PMID 28321286, 2017).
brain tumor (1 paper, 2017). "While the contribution of this mutation to the pathogenesis of the tumor is not known at this time, a role of AUTS2 in deregulation of PRC1 can be a part in tumorigenesis of a brain tumor." (PMID 29445462, 2017).
colon cancer (1 paper, 2017). "In colon cancer cell lines NKX2-3 regulates AUTS2 as well, suggesting a direct regulatory connection." (PMID 28151996, 2017).
Crohn disease (1 paper, 2023). A gastrointestinal disorder characterized by chronic inflammation involving all layers of the intestinal wall, noncaseating granulomas affecting the intestinal wall and regional lymph nodes, and transmural fibrosis. "A genome-wide association study reported a downregulated expression of AUTS2 in endoscopic pinch biopsies of Crohn’s disease (CD) patients compared to healthy individuals." (PMID 38274809, 2023).
fibrosis (1 paper, 2016). the formation of excess fibrous connective tissue in an organ or tissue in a reparative or reactive process. "Deeper analysis of differential gene expression over the dose-response range that results in sublethal vs. lethal pneumonitis/fibrosis, identified only three genes associated with the threshold for lethality in both strains- Retnla, Gria1, and Auts2." (PMID 27845360, 2016).
hepatocellular carcinoma (1 paper, 2021). A malignant tumor that arises from hepatocytes. "Simultaneously, we predict that two genes (AUTS2 and SLAIN1) regulated by miR-1246 are very lowly expressed in hepatocellular carcinoma, and the high expression of the AUTS2 gene among them is correlated with the longer overall survival time of hepatocellular carcinoma patients." (PMID 34163524, 2021). "CASK and AUTS2 genes have not yet been reported on the mechanism of their involvement in hepatocellular carcinoma." (PMID 34163524, 2021).
NK-cell leukemia (1 paper, 2019). "But we detected no AUTS2 mutations as we have recently described in NK-cell leukemia cell lines." (PMID 31143370, 2019).
pancreatic cancer (1 paper, 2017). "AUTS2 has also been shown to be a potential therapeutic target for pancreatic cancer with liver metastasis." (PMID 29215599, 2017).
Parkinson disease (1 paper, 2020). A progressive degenerative disorder of the central nervous system characterized by loss of dopamine producing neurons in the substantia nigra and the presence of Lewy bodies in the substantia nigra and locus coeruleus. "Although further investigations are required to assess how loss of Auts2 reduces dopaminergic neurons in the midbrain, our findings provide insights into a potential role of AUTS2 in the onset or progression of Parkinson disease or extrapyramidal disorder." (PMID 33305180, 2020).
renal carcinoma (1 paper, 2017). A carcinoma arising from the epithelium of the renal parenchyma or the renal pelvis. "Thus, further studies are warranted to elucidate the role of MAPT and AUTS2 in renal cancer." (PMID 29215599, 2017).
Rubinstein-Taybi syndrome (1 paper, 2023). A rare malformation syndrome characterized by congenital anomalies (microcephaly, specific facial characteristics, broad thumbs and halluces and postnatal growth retardation), short stature, intellectual disability and behavioral characteristics. "Furthermore, impairment in AUTS2 and P300 interaction was found in developmental disorders, including Rubinstein-Taybi syndrome." (PMID 36751888, 2023).